CXADR (CXADR cell adhesion molecule)
Diseases named in the same sentence as CXADR in open-access papers (continued):
Sharing a sentence is not in itself a finding about the gene and the disease.
lung carcinoma (1 paper, 2022). "These integrated results from genetic association and eQTL analysis suggested rs208908 had different risk effect in lung cancer between men and women through CXADR gene expression regulation in lung tissues." (PMID 35138370, 2022). "For example, the difference in allele frequency for rs208908, as a key variant in a TF binding site, may cause differential regulation of TFs between sexes, and then differential CXADR gene expression and different lung cancer risk between men and women." (PMID 35138370, 2022).
measles (1 paper, 2023). A highly contagious viral infection caused by the measles virus. "EFNB2 is a receptor for Hendra and Nipah virus, CD4 for human immunodeficiency virus, CXADR is the coxsackievirus and adenovirus receptor, and BSG has been shown to be involved in infection of measles and human cytomegalovirus." (PMID 38140653, 2023).
myocardial infarction (1 paper, 2020). Gross necrosis of the myocardium, as a result of interruption of the blood supply to the area, as in coronary thrombosis. "Similar to CXADR, ICAM-1 is a virus receptor, for rhinoviruses, which cause respiratory infections but have been linked to myocardial infarction." (PMID 32852032, 2020).
nephrotic syndrome (1 paper, 2015). A collection of symptoms that include severe edema, proteinuria, and hypoalbuminemia; it is indicative of renal dysfunction. "Indeed, using an established genetic model of nephrotic syndrome (Cd2ap knockout animals) and sheep derived nephrotoxic serum (NTS), we could demonstrate that in both conditions tested, CXADR was strikingly up-regulated." (PMID 26076477, 2015).
periodontitis (1 paper, 2022). An acute or chronic inflammatory process that affects the tissues that surround and support the teeth. "Hence, elucidation of risk factors of periodontitis that have effects on JAM1- or CXADR-protein modification is considered to helpful to better understand its etiology." (PMID 35211692, 2022).
prostate carcinoma (1 paper, 2017). A carcinoma that arises from epithelial cells of the prostate gland. "In respect to other prostate cancer cell lines, DU-145 human androgen-independent prostate cancer cells also expressed CXADR, but PC-3, another androgen-independent prostate cancer cell line, did not." (PMID 28074864, 2017). "We developed monoclonal antibodies against human CXADR and found that one antibody (6G10A) significantly inhibited the growth of subcutaneous as well as orthotopic xenografts of human prostate cancer cells in vivo." (PMID 28074864, 2017). "While AR-negative DU-145 cells also expressed CXADR, PC-3, another AR-negative prostate cancer cell line, did not." (PMID 28074864, 2017).
Sepsis (1 paper, 2025). Sepsis is defined as life-threatening organ dysfunction caused by a dysregulated host response to infection. "Firstly, the presence of CXADR deletion prior to endotoxin challenge is impossible in the clinical setting of sepsis." (PMID 41311862, 2025).
tumor (27 papers, 2003 to 2025). "Also, the downregulation of one of our long survival marker genes, CXADR, encoding a tight junction protein, may enhance tumor progression by promoting EMT." (PMID 32053263, 2020). "Studies have reported that physiological abnormalities such as cardiac failure, impairment in spermatogenesis, and tumour development are related to altered CXADR levels." (PMID 36674801, 2023). "CXADR is known as a key regulator of adhesion and inflammation and has been shown to have both oncogenic and tumor suppressive functions depending on the type of cancer." (PMID 35954313, 2022). "The upregulated genes, including WNT11, HAPLN1, FGF10, BBOX1, CXADR, NDP, and EREG are associated with tumor proliferation, migration, and cancer stemness." (PMID 35954313, 2022). "In this paper, we fully describe the development of a novel CXADR antibody and its anti-tumor activity in vitro and in vivo in detail." (PMID 28074864, 2017). "Some normal tissues, such as liver and pancreas, expressed CXADR at marginal levels compared to tumor tissues and cancer cells, but normal testis expressed it at levels comparable to cancer cells." (PMID 28074864, 2017). "To create a new anti-tumor antibody, we conducted signal sequence trap by retrovirus-meditated expression method and identified coxsackie virus and adenovirus receptor (CXADR) as an appropriate target." (PMID 28074864, 2017). "Knockdown and overexpression of CXADR confirmed the dependence of its anti-tumor activity on CXADR expression." (PMID 28074864, 2017). "In contrast, our results suggest that CXADR is highly expressed in tumor tissues of prostate, lung, and brain." (PMID 28074864, 2017). "We previously reported the strategy for the construction of antibodies against CXADR and the preliminary results of their anti-tumor effects in EORTC-NCI-AACR Symposium on Molecular Targets and Cancer Therapeutics10." (PMID 28074864, 2017). "Our present results show that anti-CXADR antibody 6G10A exerts potent anti-tumor activity primarily through both ADCC and CDC activities." (PMID 28074864, 2017). "Taken together, these results have clearly shown that our anti-CXADR antibody 6G10A has great potential as an anti-tumor drug." (PMID 28074864, 2017). "Although it did not affect the growth of xenograft tumor of MKN-7 cells transfected with a control vector, 6G10A did inhibit the tumor growth of MKN-7 cells expressing CXADR and also CXADR iso5." (PMID 28074864, 2017). "We then assessed the anti-tumor effect of anti-CXADR antibody 6G10A against xenograft models of these three cancer cell lines." (PMID 28074864, 2017). "We then examined the anti-tumor effect of 6G10A against these transfectants that overexpressed CXADR." (PMID 28074864, 2017). "We examined the expression levels of CXADR protein in several normal and tumor tissues using a commercially available antibody against CXADR." (PMID 28074864, 2017). "We examined lysates of various tissues and found that CXADR was expressed in tumor tissues of prostate, lung, and brain at higher levels than in respective normal tissues." (PMID 28074864, 2017). "In addition, it has been reported that CXADR expression alters during tumor development; however, the alteration of CXADR expression seems to be tumor specific." (PMID 36674801, 2023). "We chose CXADR as a target for the development of anti-tumor antibodies because CXADR has not been clearly linked to cancer." (PMID 28074864, 2017). "Moreover, 6G10A reacted with human tumor tissues, such as prostate, lung, and brain, each of which express CXADR." (PMID 28074864, 2017). "Thus, our results clearly showed that the anti-tumor activity of 6G10A depends on the expression of CXADR on cancer cell surface." (PMID 28074864, 2017). "We intend to evaluate CXADR expression in various tumor tissues in a future study." (PMID 28074864, 2017). "We next examined the anti-tumor activity of anti-CXADR antibodies in vivo using xenograft models." (PMID 28074864, 2017).
tumor (continued). "ThyroidPrint® is a novel q-PCR-based ten-gene classifier with its signature representing both the tumor microenvironment (CXCR3, CXCL10, CCR3, CCR7, and CXADR) and tumor epithelial cells (TIMP1, CLDN1, KTR19, AFAPL2, and HMOX1)." (PMID 37671897, 2023). "Particularly, our recent finding that CXADR is required for adherens junction (AJ) and TJ assembly during porcine blastocyst formation (Kwon, Kim & Choi, 2016) also supports this hypothesis, because CXADR was reported to be directly associated with ROCK in human tumor cells." (PMID 27077008, 2016). "This also indicates that the expression level of CXADR would not further increase with the progression of the tumor." (PMID 37243239, 2023). "We showed that 6G10A failed to exert anti-tumor activity against cancer cells when CXADR was downregulated." (PMID 28074864, 2017). "When we assessed the anti-tumor effect of 6G10A in vivo, we found that it failed to inhibit the growth of DU-145 tumor cells that lacked CXADR expression." (PMID 28074864, 2017). "Recently its has been shown that CXADR was highly expressed in tumor tissues rather than normal tissues and the anti-CXADR antibody could be a feasible drug candidate against cancer disease." (PMID 29190716, 2017). "No marker fulfilled all these criteria for pCAF subtype D (CXADR and MEOX were strongly expressed by tumour cells; PLS1 by endothelial cells)." (PMID 30575030, 2019).
cancer (17 papers, 2010 to 2025). A tumor composed of atypical neoplastic, often pleomorphic cells that invade other tissues. "CXADR expression has also been associated with cancer stem cell phenotype and resistance to chemotherapy." (PMID 35954313, 2022). "Here our results indicate that LNX1 suppresses cancer stemness which partially requires the downregulation of CXADR." (PMID 29190716, 2017). "We chose CXADR as a target for further studies because there were few reports about the role of CXADR on cancer development." (PMID 28074864, 2017). "In order to confirm the physiological target of 6G10A, we constructed cancer cells with knockdown or overexpression of the CXADR gene." (PMID 28074864, 2017). "Expression of CXADR in DU-145 cancer cells was suppressed by transfection of a CXADR shRNA expression vector." (PMID 28074864, 2017). "However, for cancer cells that poorly express CXADR, the oncolysis efficiency of OAd5 is also very low." (PMID 37243239, 2023). "Although precise mechanistic pathways in cancer remains poorly understood, the emerging role of CXADR in tumorigenesis has been reported, including control of cell–cell adhesion, recruitment of immune cells, and inducer of the epithelial to mesenchymal transition." (PMID 35954313, 2022). "Considering the fact that CXADR is deregulated in various cancer and inflammatory conditions, we hypothesized that CXADR expression might be induced during plaque formation in arteries." (PMID 32852032, 2020). "Although we need further evaluation of its reactivity and safety in human tissues, our results show that a novel anti-CXADR antibody may be a feasible candidate for cancer immunotherapy." (PMID 28074864, 2017). "Furthermore, the coxsackievirus and adenovirus receptor (CXADR) was found to be one critical downstream mediator of cancer stemness regulated by LNX1." (PMID 29190716, 2017). "There are few studies about the role of CXADR in cancer biology." (PMID 28074864, 2017). "Thus, the function of CXADR in cancer development is controversial." (PMID 28074864, 2017). "Next, we examined subcellular localization of CXADR, which was recently reported to be required for adherens and tight junction formation during porcine blastocyst development (Kwon, Kim & Choi, 2016) and shown to directly associated with ROCK1 and ROCK2 in human carcinoma cells." (PMID 27077008, 2016). "The high expression of CXADR and PTTG1 in cancer is significantly correlated with the short OS and DSS, further demonstrating the close relationship between the two factors." (PMID 37243239, 2023). "Regarding CXADR as a target for 6G10A, overexpression of CXADR isoform 1 as well as isoform 5 rendered MNK-7 cancer cells sensitive to 6G10A." (PMID 28074864, 2017). "Although CXADR may be a protective factor according to the survival analysis, it is upregulated in metastatic TNBC and cancer tissue, which suggests the possibility of a false discovery in the survival analysis." (PMID 32596149, 2020). "In this study, however, knockdown and overexpression of CXADR did not drastically suppress or increase the growth of cancer cells in vitro." (PMID 28074864, 2017). "6G10A significantly inhibited the growth of xenograft tumors of each of the CXADR-expressing cancer cell lines without any severe adverse effect on host mice." (PMID 28074864, 2017). "Since we could not exclude the possibility that the dependence of CXADR on cell growth or survival might differ among cell lines, further investigation is required to elucidate the precise role of CXADR on cancer cell growth." (PMID 28074864, 2017).
infection (14 papers, 2003 to 2025). The state of being infected such as from the introduction of a foreign agent such as serum, vaccine, antigenic substance or organism. "Future experiments are needed to determine if the overall decrease in CXADR (the gene that encodes the receptor for coxsackievirus) during infection is transcriptionally regulated or is a consequence of virus-mediated cell death." (PMID 32093375, 2020). "After two months of infection, the number of viral genomes was determined and the relative level of mRNA for CXADR, BNIP3, SPARCL1 and SLFN11 was measured in infected and mock-infected cells." (PMID 41497616, 2025). "In agreement with previously reported results, infection reduced CXADR, BNIP3, and SPARCL1 expression to between 0.6% and 13% of the level detected in non-infected cells transduced with the empty vector." (PMID 41497616, 2025). "An interpretation of our results is that M1 macrophages and foam cells in plaques are susceptible to infection with CVB and other enteroviruses using CXADR as a receptor." (PMID 32852032, 2020). "CXADR Ig-like cell adhesion molecule may play critical roles in the response to infection in primary bovine mammary gland epithelial cell." (PMID 32777913, 2021). "Levels of CXADR, BNIP3, and SPARCL1 mRNA were measured during the persistent phase of infection with Ad5dl309 (56–77 days p.i.)and normalized to the housekeeping gene EIF1." (PMID 41497616, 2025). "We previously reported that expression of several cellular genes, including CXADR, BNIP3, SPARCL1, SLFN11, BBS9 and BNIP3, is significantly downregulated by epigenetic means during the persistent phase of infection of B cells." (PMID 41497616, 2025). "For example, in constructing a mass-action model of cardiomyocyte infection by coxsackievirus B3 (CVB3), RNA-seq was used to estimate abundances of the serial CVB3 receptors, CD55 and CXADR." (PMID 39333715, 2024).
heart (1 paper, 2025). "We demonstrated that CXADR has anti-inflammatory and cardioprotective effects in endotoxin-induced failing heart characterized by IL-17 A-mediated inflammatory responses, besides its role as an inflammatory mediator." (PMID 41311862, 2025).
heart diseases (1 paper, 2025). "The targeted manipulation of CXADR expression would open new possibilities for therapeutic interventions in various heart diseases." (PMID 41311862, 2025).
CXADR also shares sentences with these, for which no sentence is quoted: glioma (2 papers); Intellectual disability (2); ovarian carcinoma (2); adenocarcinoma (1); aspergillosis (1); bladder cancer (1); brain tumor (1); cervical spondylosis (1); Cognitive impairment (1); hepatocellular carcinoma (1); infarction (1); lung adenocarcinoma (1); lymphoma (1); malignant glioma (1); metabolic disorders (1); microcephaly (1); Miscarriage (1); myocardial diseases (1); myotubular myopathy (1); preeclampsia (1); respiratory infections (1); scoliosis (1); Stiff-Man syndrome (1); Stroke (1); Thrombocytopenia (1).